INS (insulin)
Diseases named in the same sentence as INS in open-access papers (continued):
Sharing a sentence is not in itself a finding about the gene and the disease.
diabetes (continued). "Our results were consistent with these 2 studies that early initiation of insulin after metformin failure, as compared with glimepiride, had high risk of all-cause mortality, CV and noncardiovascular death, after adjusting for all comorbidities and diabetes severity in a Chinese population." (PMID 33655987, 2021). "Diabetes mellitus (DM) is a chronic hyperglycaemia caused by defective insulin secretion, defective insulin action, or both." (PMID 35052549, 2021). "Therefore, this highlights the possibility that vitamin D3 levels might be a good indicator for diabetes since low vitamin D3 levels may cause insulin resistance and impaired β-cell function in the pancreas." (PMID 34371798, 2021). "Due to the loss of responsiveness to insulin, diabetes mellitus (DM) patients develop increased platelet reactivity and reduced response to antiplatelet agents." (PMID 34609028, 2021). "Insulin sensitivity is closely related to obesity, and two of the strongest independent risk factors are waist circumference and body fat percentage, which maybe is more pronounced in individuals with diabetes." (PMID 34886380, 2021). "Type 1 diabetes mellitus (T1DM), also historically known as juvenile or insulin-dependent diabetes, is the most predominant type of DM in children and adolescents, being caused by insufficient pancreatic insulin production." (PMID 34577791, 2021). "Diabetes mellitus (DM), as a kind of metabolic disease, is characterized by the deficiency of insulin function and secretion, which leads to chronic hyperglycaemia, affecting the metabolism of protein, fat and carbohydrate." (PMID 33300675, 2021). "To check whether diabetes also causes fibrosis and morphological changes in other insulin sensitive organs, such as adipose tissue and liver, we performed similar staining experiments on the tissue sections of these organs, as was done on pancreas and skeletal muscles." (PMID 34155273, 2021). "Thus, the dysregulation of insulin signaling caused by elevated stress conditions, aging, or other environmental insults can have major pathological consequences including neurodegeneration, muscle wasting, and diabetes." (PMID 33398091, 2021). "However, the thrifty phenotype hypothesis proposed poor nutrition in early life could produce altered glucose–insulin metabolism, which increases susceptibility to development of type 2 diabetes mellitus." (PMID 34444226, 2021). "Hence, concomitant hyper activation of mTORC1 in liver, muscle, adipose fat and beta-cells may account for the close association between peripheral insulin resistance and insulin hypersecretion during the pre-diabetes stage of T2D." (PMID 34659123, 2021). "Moreover, high endogenous insulin concentrations observed in patients with type 2 diabetes mellitus are associated with reduced hepatic synthesis of IGFBP-1 (the main IGF-1 binding globulin), leading to increased bio-availability of IGF-1 and possible enhancement of its known mitogenic effects." (PMID 34680546, 2021). "Lifestyle interventions, such as diet, exercise, and weight loss, are critical to controlling diabetes and preventing progression and are considered first-line treatments; however, success with these interventions is often limited, necessitating medication escalation which often includes insulin." (PMID 34458301, 2021). "Also, lower mean testosterone in the participants who receive insulin confirms the association of diabetes with testosterone and is consistent with the results of the previous studies suggesting the relationship between insulin resistance and low testosterone levels." (PMID 33842826, 2021). "Diabetes mellitus (DM) is a metabolic disease characterized by elevated levels of blood glucose caused by defects in insulin secretion or insulin resistance." (PMID 35003953, 2021). "Diabetes mellitus (DM) is a chronic metabolic disorder linked with the emission and sensitivity of insulin." (PMID 34830043, 2021).
diabetes (continued). "However, vigorous exercise leads to increased oxidative stress, which may be associated with a decrease in insulin secretory ability and aggravates diabetes." (PMID 33547929, 2021). "Their increased presence in the pancreas of human subjects with type 1 diabetes raises the possibility that these cells could be implicated in the pathophysiology of this form of diabetes, which is due to autoimmune destruction of the insulin-secreting beta cells." (PMID 34440644, 2021). "The most striking features of HNF1α-/HNF4α-MODY are that they result in a reduced insulin secretory response to glucose but marked sensitivity to low-dose sulfonylureas and cause progressive pancreatic β-cell dysfunction and increasing hyperglycemia that leads to diabetes in early adult life." (PMID 34746319, 2021). "diabetes is typically characterized by an abnormal increase in glucose levels caused by one or two mechanisms: inadequate insulin production by the pancreas or inadequate cell sensitivity to the action of insulin caused by the reduced function of insulin receptors." (PMID 34204428, 2021). "The deterioration of mood may be a urinary tract infection in one of the patients, the persistent increase in blood pressure due to atherosclerosis seen in most patients, or the treatment of diabetes associated with intradermal insulin administration instead of oral preparations." (PMID 34360348, 2021). "Diabetes mellitus (DM) is a disease characterized by chronic hyperglycemia and impaired metabolism of carbohydrates, proteins, and lipids caused by impaired insulin secretion and action." (PMID 33639953, 2021). "Diabetes mellitus (DM) is a chronic metabolic disorder caused by insulin deficiency or impaired insulin action, which is characterized by increased blood glucose levels (hyperglycemia)." (PMID 34702288, 2021). "Diabetes mellitus, commonly identified as diabetes, is a cluster of metabolic disorders that are distinguished by high blood glucose levels over a prolonged period of time and associated with inadequate production of insulin by the pancreatic β-cells and insulin resistance." (PMID 34207217, 2021). "Therefore, changes in lipogenesis and fatty acid profile in the hypothalamus may be associated with modifications in insulin sensitivity, central inflammation and diabetes development." (PMID 34440853, 2021). "Compared with type 2 DM, monogenic diabetes, including maturity-onset diabetes of the young (MODY), is a rare form of DM caused by mutations in one of more than 20 genes that control either the secretion or action of insulin." (PMID 33663443, 2021). "It is clinically implicated that hyperinsulinemia or diabetes could be one of the risk factors inducing breast cancers and that the active insulin pathway could also facilitate the progression and metastasis of breast cancer via providing excessive nutrients and pro-survival signals." (PMID 34575098, 2021). "Diabetes mellitus (DM) is a chronic disease caused by dysfunctional use, or the lack, of insulin and resulting in impaired blood glucose regulation." (PMID 33544228, 2021). "However, a low insulin secretion capacity could increase risk of developing diabetes if challenged by insulin resistance from unhealthy diets or decreased physical activity as seen during the nutrition transition." (PMID 33740034, 2021). "In this proof-of-concept study, we hypothesized that the AAC2 nanofibers with surface-bound insulin could induce combinatorial effects on the regulation of glucose metabolism in peripheral and nervous tissues and mitigate cognitive decline in mice with insulin-deficient diabetes." (PMID 35056977, 2021). "In its two main forms, diabetes is caused by immune-mediated beta-cell destruction (type 1 diabetes (T1D)) or by the loss of physiological beta-cell functional mass, often concomitant to reduced insulin sensitivity in peripheral insulin-dependent tissues (type 2 diabetes (T2D))." (PMID 33546278, 2021).
diabetes (continued). "Diverse dominant mutations in the human insulin gene (INS) have been identified associated with diabetes mellitus (DM)." (PMID 34659132, 2021). "Similar fast effects could only be seen after Roux-en-Y gastric bypass surgery where diabetes remission was accompanied by the normalisation of fasting insulin levels within a few days before significant weight loss occurred and although patients were still obese." (PMID 33922802, 2021). "Abnormalities of insulin signaling transduction account for the development of insulin resistance which plays a mechanistic role in the pathogenesis of several CV risk factors such as diabetes, metabolic syndrome, hypertension, atherosclerosis, obesity, and non-alcoholic fatty liver disease (NAFLD)." (PMID 32737757, 2021). "It should be noted that abnormal glucose regulation may begin more than 10 years before the diagnosis of type 2 diabetes mellitus with the development of obesity-associated insulin resistance, which is defined as an impairment in the ability of insulin to maintain glucose homeostasis." (PMID 34445261, 2021). "Thus, there is a dual islet abnormality in diabetes, qualitatively common to both type 1 and type 2: The deficiency of insulin secretion in response to hyperglycemia, and the deficiency of glucagon secretion in response to the lowering of blood glucose by insulin." (PMID 34572493, 2021). "Also, a large group of patients reported nephropathy, a conventional risk factor for hypoglycemia in people with diabetes, due to multiple factors as the decrease of insulin clearance and it’s degradation in peripheral tissues, reduction in glycogen stores, reduced renal gluconeogenesis." (PMID 33402217, 2021). "Diabetes mellitus (DM) is a metabolic disorder associated with chronic hyperglycemia that occurs as a result of impaired insulin secretion and/or insulin resistance." (PMID 35048037, 2021). "Notably, the primary cause of diabetes is insufficient insulin secretion, whether absolute or relative." (PMID 34609028, 2021). "Diabetes mellitus (DM) is a chronic metabolic disorder caused by insufficient production of insulin or insulin resistance, which results in elevated blood glucose levels." (PMID 33800470, 2021). "In other tissues, β-pancreatic cells have impaired insulin release when ROS production is induced by a high concentration of Pi, strengthening the hypothesis that individuals with hyperphosphataemia have an increased risk of developing diabetes." (PMID 34360534, 2021). "In addition, fibroblasts from a PNDM patient harboring an intronic INS mutation have been efficiently generated and may serve as a diabetes model to characterize the expected aberrant splicing." (PMID 34079523, 2021). "A reduction in hepatic fat content could potentially exert beneficial effects on e.g. hepatic inflammation and fibrosis, however, some retrospective studies have indicated an association between insulin therapy in diabetes and increased risk of hepatic fibrosis and hepatocellular cancer." (PMID 33596938, 2021). "Diabetes burnout, a state of exhaustion towards the condition associated with lack of treatment adherence and deficient blood glucose control, may also result in omission of insulin." (PMID 34121470, 2021). "Higher levels of plasma POA may be a distinctive feature of the HLZ and a sign of a favourable metabolism since it is associated with enhanced insulin sensitivity, decreased lipid accumulation in the liver, and significant amelioration or prevention of diabetes." (PMID 33650014, 2021). "Diabetes mellitus is characterized by an altered metabolism (of carbohydrates, lipids, and lipoproteins) and chronic hyperglycemia resulting from pancreatic β-cell dysfunction, insulin production deficiency, insulin resistance in key target tissues and impaired glycemic index control." (PMID 34045956, 2021).
diabetes (continued). "The American Diabetes Association defines diabetes mellitus (DM) as a group of metabolic diseases characterised by hyperglycaemia resulting from defects in insulin secretion, insulin action, or both." (PMID 34356210, 2021). "Diabetes mellitus (DM) is a class of metabolic disorders caused by the impairment of metabolism in insulin secretion or resistance." (PMID 34063621, 2021). "In conclusion, we could show that in patients with type 2 diabetes mellitus, insulin therapy is related to an increased risk of being diagnosed with pneumonia and that there is no antidiabetic drug therapy in the present study which is related to a lower risk of being diagnosed with pneumonia." (PMID 34683125, 2021). "Diabetes mellitus (DM) is described as chronic hyperglycemia because of a deficiency in either insulin secretion (type 1 DM) or insulin activity (type 2 DM) or both." (PMID 34497854, 2021). "Moreover, our work indicates that Mg supplementation may improve insulin-sensitivity parameters in those at high risk of diabetes." (PMID 34836329, 2021). "Physical inactivity decreases insulin sensitivity which may cause diabetes." (PMID 33532605, 2021). "While surgery could be definitively curative for focal forms, near-total pancreatectomy, reserved for diffuse forms unresponsive to available drugs, could cause iatrogenic diabetes and allocate patients to life-long pancreatic enzyme replacement and insulin therapy." (PMID 34408725, 2021). "However, diabetic ketoacidosis is a serious complication of diabetes caused by low insulin levels." (PMID 33920838, 2021). "Diabetes mellitus (DM) is an emerging health burden caused due to deficiency of production of insulin and/or resistance to insulin." (PMID 33628307, 2021). "Diabetes mellitus (DM) is an endocrine disorder characterized by hyperglycemia, polyuria, polydipsia, and weight loss due to a defect in insulin secretion and/or action." (PMID 34124187, 2021). "Type 2 diabetes, which accounts for 90–95% of all cases of DM, occurs due to a progressive loss of β-cell insulin secretion frequently on the background of insulin resistance compensated by increased secretion of insulin." (PMID 34182970, 2021). "In addition, the insulin injection therapy represents a chronic and costly burden for diabetic patients, and it does not entirely eliminate the risk of acute and chronic complications related to diabetes." (PMID 34589059, 2021). "Many studies have linked their high consumption with an improvement in insulin sensitivity, blood lipid profile, and a reduction in systolic and diastolic blood pressure levels, in line with the standards of medical care established by the American Diabetes Association." (PMID 33918177, 2021). "In addition, it has been shown that Asian populations develop diabetes at a younger age, require insulin treatment more often, and see an increased risk of cancer compared to Western populations, which may explain the higher number of PC cases." (PMID 33467667, 2021). "Diabetes mellitus (DM) is a metabolic disorder that results either from loss of insulin generating cells in the pancreas or reduced sensitivity of the tissues to insulin." (PMID 34014991, 2021). "They reported ethnic differences in the optimal points in the canalization of normal blood glucose levels, and speculated that East Asians were more susceptible to diabetes, and a small change in insulin resistance may lead to drastic variations in their β-cell function." (PMID 34917033, 2021). "Insulin resistance (IR) is defined as a lower-than-expected response to insulin action from target tissues, resulting in the impairment of both glucose and lipid metabolism at different levels and predisposing to the development of type 2 diabetes mellitus (T2DM)." (PMID 33800465, 2021).
diabetes (continued). "A study indicated that two miRNAs, miR-106b-5p, and miR-222-3p, contribute to bone morrow transplantation (BMT)-induced beta-cell regeneration in mouse models of insulin-deficient diabetes, which may lead to the development of new therapeutic tools for diabetes." (PMID 33324409, 2020). "Likewise, increased IMAT is associated with reduced insulin sensitivity in obesity and diabetes." (PMID 33375333, 2020). "AMPK-mediated pioglitazone signaling results in an increase in insulin-stimulated glucose disposal, enhanced expression of the genes encoding adiponectin receptors, and coding for factors connected with mitochondrial function and FA oxidation in the muscles of patients with diabetes." (PMID 32708786, 2020). "Thus, impaired insulin action in these tissues causes the hyperglycemia that occurs in diabetes." (PMID 33150239, 2020). "Therefore, blood sugar levels are elevated as a consequence of diabetes, which may itself be caused in different ways including exposure to chemicals such as endocrine disruptors, which affect insulin production." (PMID 32604970, 2020). "In addition, Cd was inversely associated with years of diabetes, insulin use and serum HbA1c." (PMID 32751456, 2020). "Hence, again an intergenerational risk for impaired insulin secretion and diabetes could be assessed and linked to ancestral BPA exposure." (PMID 32398147, 2020). "Emerging adults complete fewer blood glucose checks per day and are more likely to miss insulin doses than older adults, a pattern of diabetes management associated with elevated hemoglobin A1c (HbA1c) levels, the standard measure of glycemic control, and diabetes disease control." (PMID 33079068, 2020). "Diabetes mellitus (DM) is characterized by high blood glucose levels due to relatively deficiency in both insulin action and secretion." (PMID 32595495, 2020). "In addition, the induction of ROS in DBMSCs by glucose may program these cells into insulin producing cells with ability to counteract inflammation and infection associated with diabetes." (PMID 32077075, 2020). "Diabetes mellitus (DM) is a metabolic disease caused by insulin resistance or defect of insulin secretion resulting in hyperglycemia." (PMID 32908567, 2020). "However, a subset of patients displays defective insulin secretion despite near-normal insulin sensitivity and monogenic forms of the diabetes (maturity onset diabetes of the young; MODY) involve mutations in genes which impact β-cell function with unaltered insulin action." (PMID 33628198, 2020). "The chronic progressive disease diabetes mellitus (DM) is associated with elevated blood glucose level (hyperglycemia) caused by impaired insulin production, impaired insulin function, or both." (PMID 32908934, 2020). "In addition, emerging evidence suggests dysfunctions of integrin-mediated adhesions in diabetes that either affect regulated insulin release in vitro or can be linked to altered actin remodeling and FAK phosphorylation in β-cells derived from diabetes type 2 patients." (PMID 32934005, 2020). "In addition, models A and B with basic and non-invasive prediction factors could be used to identify high-risk diabetes cases that require a test for fasting insulin, blood glucose or HBA1c levels." (PMID 32881911, 2020). "The fact that IDE may degrade insulin, amylin, and Aβ suggests that AD may be linked to diabetes via chromosome 10 and the finding that Aβ plaque size correlates inversely with IDE expansion and activity suggests that IDE deficiency may mediate plaque accumulation and cognitive impairment in AD." (PMID 32503113, 2020). "Diabetes mellitus (DM) is a complex metabolic disorder resulting either due to relative or absolute deficiency of pancreatic insulin secretion or insensitivity to insulin action, ensuing in postprandial hyperglycemia and assorted diabetic complications." (PMID 32789301, 2020).